ANXA5 (annexin A5)
Diseases named in the same sentence as ANXA5 in open-access papers (continued):
Sharing a sentence is not in itself a finding about the gene and the disease.
infection (298 papers, 2005 to 2026). The state of being infected such as from the introduction of a foreign agent such as serum, vaccine, antigenic substance or organism. "For example, stresses from weaning, transport, and commingling reduced the expression level of the ANXA5 (hub–hub gene) and, thus, lead to an increase in apoptotic cells in the lungs or epithelial lining fluid, which can increase the susceptibility of cattle to a primary infection." (PMID 34733317, 2021). "Only a single pro-apoptotic protein, ANXA5, was higher in abundance after infection with huH1N1 in lower trachea, and the anti-apoptotic DFFA was lower in abundance in upper trachea." (PMID 39247193, 2024). "The interaction between ANXA5 and influenza virus appears to be essential for successful infection, similar to the interaction of ANXA2 with the human cytomegalovirus (CMV), human papilloma virus type 16 (HPV16) and enterovirus 71 (EV71)." (PMID 35176125, 2022). "Earlier experiments reported that the addition of ANXA5 to an infection of H. pylori with the gastric epithelial cell line AGS resulted in a ~20% decrease of CagA translocation." (PMID 35176125, 2022). "SP-A2 mice showed higher levels of annexin A5, SP-A, 14-3-3 zeta protein, and glutathione S-transferase A4 than SP-A1 and KO mice in response to ozone and infection." (PMID 30972061, 2019). "AnxA5 may thereby exert multiple protective effects during infection, particularly EHEC infection, reducing circulatory harmful prothrombotic toxin-positive EVs and decreasing the inflammatory response to infection." (PMID 34073384, 2021). "However, the C. pneumoniae staining pattern in MF that were infected in the presence of PS- masking AnxA5 revealed less and smaller inclusions similar to the staining we observed after direct infection of macrophages." (PMID 19547701, 2009). "Apoptosis related proteins (ANXA5 and Caspase-13/CASP4) and CAPN14, USP18, XAF1, Caspase-13/CASP4, and ISG12 transcripts were significantly upregulated after infection with swH1N1 compared to controls." (PMID 39247193, 2024). "The binding of phosphatidylserine and non-phospholipid components of the HBV envelope to ANXA5 also contributes to the infection process." (PMID 40717977, 2025). "As we could show that anxA5 delayed disease in the EHEC mouse model, we suggest that anxA5 be investigated as a potential treatment for this infection." (PMID 34073384, 2021). "Nevertheless, TLR4-MD2 specific stimulation in the reporter cell line could be significantly inhibited with ANXA5 in the re-isolates, but not in the pre-infection strain." (PMID 35176125, 2022). "Notably, several members from Annexin A family (ANXA1, ANXA2, ANXA4, ANXA5 and ANXA6) were overrepresented in DEVs from Lm-infected BMDCs but remained unaltered in total cell lysates, suggesting a specific sorting during infection of these ANXA family members to EVs." (PMID 36131943, 2022). "In rat hepatocyte primary cultures, ANXA5 promotes HBV entry, facilitating successful infection, while in human hepatocyte primary cultures, ANXA5 does not prevent HBV infection." (PMID 40717977, 2025).
cardiovascular disease (12 papers, 2013 to 2024). "For cardiovascular disease, anxA5 was reported to reduce inflammation in advanced atherosclerotic plaques and to attenuate plaque progression in early disease." (PMID 34405304, 2021).
heart (1 paper, 2012). "The pathophysiologcal significance of an increase in circulating AnxA5 in this adult congenital heart population, however, requires further clarification." (PMID 23284897, 2012).
inflammation (1 paper, 2017). Aberrant reaction of the microcirculation characterized by movement of fluid and leukocytes from the blood into extravascular tissues. "Therapeutic activity of AnxA5 has been shown in various mouse models of vascular inflammation." (PMID 29267398, 2017).
ANXA5 also shares sentences with these, for which no sentence is quoted: leukemia (83 papers); pancreatic cancer (66); myeloma (30); breast tumor (13); sarcoma (13); endometriosis (10); multiple myeloma (10); renal carcinoma (10); lentivirus infection (9); adenocarcinoma (7); brain tumor (7); esophageal cancer (7); triple-negative breast carcinoma (7); bacterial infection (6); Burkitt lymphoma (6); head and neck cancer (6); medulloblastoma (6); promyelocytic leukemia (6); squamous cell carcinoma (6); acute lymphoblastic leukemia (5); acute myocardial infarction (5); astrocytoma (5); brain cancer (5); breast adenocarcinoma (5); chondrosarcoma (5); co-infection (5); meningioma (5); head and neck squamous cell carcinoma (4); HIV-1 infection (4); Infertility (4).
A further 237 diseases each share a sentence with ANXA5 in 4 papers or fewer.